CHURC1-FNTB (CHURC1-FNTB readthrough)
Synonyms: FTase-beta
Gene: Protein-coding gene on chromosome 14 (64,914,485 to 65,061,803, forward strand). Ensembl gene ENSG00000125954.
Genetic constraint (gnomAD): Loss-of-function variants: 36 observed, 60.58 expected, observed/expected ratio (o/e) 0.59, 90% interval 0.46 to 0.79. The upper end of that interval is the gene's LOEUF score, 0.79, which puts it in group 3 of 6, group 1 being the genes least tolerant of losing a copy. Missense variants: 441 observed, 563.42 expected, observed/expected ratio (o/e) 0.78, 90% interval 0.72 to 0.85. Synonymous variants: 220 observed, 216.57 expected, observed/expected ratio (o/e) 1.02, 90% interval 0.91 to 1.14.